CD47 (CD47 molecule)
Diseases named in the same sentence as CD47 in open-access papers (continued):
Sharing a sentence is not in itself a finding about the gene and the disease.
glioblastoma (continued). "Besides, the combination of Dox@HFn GelL with anti‐CD47 antibody (αCD47) inhibits postsurgical tumor recurrence of aggressive orthotopic glioblastoma tumor model and significantly extends mice survival." (PMID 38029345, 2024). "The augmentation of macrophage phagocytosis of tumor cells has been observed in various preclinical tumor models, such as small-cell lung cancer, anaplastic thyroid carcinoma, and glioblastoma, through the implementation of monoclonal antibodies or fusion proteins to obstruct the CD47/SIRPα axis." (PMID 38532108, 2024). "Furthermore, the large molecular size of anti-CD47 mAbs will likely hinder penetration into the glioblastoma TME." (PMID 38786045, 2024). "When the spatial distribution of CD47 and SIRPα mRNA is assessed within glioblastoma, both CD47 and SIRPα are expressed to a greater extent at the leading edge, indicating this may be a mechanism for immune evasion as tumor cells infiltrate the brain." (PMID 38786045, 2024). "In addition to bladder cancer, previous studies have shown that targeting CD47 and angiogenesis is also effective in inhibiting the growth of gastric cancer, glioblastoma, and non-small cell lung cancer by mediating similar mechanisms." (PMID 39335665, 2024). "The CD47 protein is highly expressed in many types of cancer, including acute and chronic myeloid leukemia, non-Hodgkin lymphomas, multiple myeloma, leiomyosarcoma, glioblastoma, and bladder, ovarian, prostate, breast, and colon carcinomas." (PMID 39795582, 2024). "Thus far, the combination of OV and CD47 blockade aiming to increase phagocytosis has proven to be successful (e.g. in glioblastoma or ovarian cancer)." (PMID 38357194, 2024). "diABZI was also tagged to CD47/PD-L1 targeting nanoparticles for intratumoral injection into a mouse glioblastoma model, leading to improved T cell infiltration in the brain and synergy with radiation delivered as 9 Gy in three fractions, using survival as the endpoint." (PMID 38659582, 2024). "Anti-CD47 therapy has demonstrated promise preclinically in glioma models and is the only immunotherapy in clinical trials, but its effectiveness will likely be limited due to variable CD47 expression in glioblastoma patients, especially in newly diagnosed cases." (PMID 38786045, 2024). "In glioblastoma models, EGFR activation induced c-Src-mediated phosphorylation of CD47, which prevented its interaction with the E3 ubiquitin ligase, TRIM21, and protected CD47 from ubiquitin-associated degradation." (PMID 37958404, 2023). "High expression of CD47 on tumor stem cells of leukemia and glioblastoma has been described." (PMID 36986829, 2023). "Furthermore, pre-clinical data suggests that the actions of anti-CD47 antibodies can be further boosted using current standard treatments for glioblastoma." (PMID 37857607, 2023). "Collectively, these findings indicated that HA plays a crucial role in macrophages polarization and CD47/SIRPα signaling between glioblastoma cells and macrophages, and suppressing the HA pathway may be a new immunotherapeutic approach for glioblastoma." (PMID 35410993, 2022). "Given that 4MU can reduce the expression of CD47 on hepatic cancer stem cells, we sought to determine whether a similar effect could be seen in glioblastoma." (PMID 35410993, 2022). "This phenomenon could be explained as follows: to protect glioblastoma cells from phagocytosis by macrophages, the reduced expression of CD47 on the glioblastoma cell surface can lead to increased expression of SIRPα in macrophages via a feedback mechanism." (PMID 35410993, 2022). "Nevertheless, given the importance of microenvironment, especially angiogenesis, in the prognosis of glioblastoma treatment, future immunotherapy against CD47 or CD24 should include the quantitative evaluations of hemodynamic changes within and surrounding the glioblastoma." (PMID 34363319, 2021). "In a human glioblastoma model, anti-CD47 therapy increased M1 macrophages within the tumor." (PMID 34944850, 2021).
glioblastoma (continued). "At present, the application of CD47 antibodies glioblastoma remains at the preclinical stage." (PMID 34363319, 2021). "Whether CD47 or CD24 is directly involved in angiogenesis within glioblastoma is unknown, this should be investigated in future studies." (PMID 34363319, 2021). "Moreover, specific inhibition of the THBS1/CD47 interaction by an antagonist peptide attenuates cell invasion glioblastoma." (PMID 34804159, 2021). "In this review, we will discuss the roles of CD47-SIRPα axis in TAMs infiltration and activities and the promising effects of targeting this axis on the activation of both innate and adaptive antitumor immunity in glioblastoma." (PMID 33329583, 2020). "Furthermore, M(GM-CSF) were found to be more phagocytic than M(IL-4 + IL-13) towards primary human glioblastoma cells in the context of CD47 blockade ex vivo." (PMID 29084248, 2017). "For instance, blocking CD47 function, using monoclonal antibodies against the CD47/SIRPα, showed in vitro and in vivo an important impact in many tumors overproducing CD47, such as leukemia and glioblastoma." (PMID 27839516, 2016). "Here, we investigated the effect of macrophage polarization on anti-CD47 antibody-mediated phagocytosis of human glioblastoma cells in vitro, as well as the effect of anti-CD47 on the distribution of M1 versus M2 macrophages within human glioblastoma cells grown in mouse xenografts." (PMID 27092773, 2016). "CD47 is consistently overexpressed in GBM, particularly in glioblastoma stem‐like cells, where it is associated with higher tumour grade, therapy resistance, and poor clinical outcomes." (PMID 41195773, 2025). "Additionally, anti-CD47 mAbs enabled human peripheral blood-derived macrophages to phagocytose patient-derived glioblastoma neurospheres in vitro, which was corroborated by decreased tumor growth in an intracranial xenograft model of glioblastoma." (PMID 38786045, 2024). "A future direction of investigation should include ascertaining if there are higher levels of CD47 expression in widely disseminated cases of diffusely infiltrating gliomas (i.e., similar to gliomatosis cerebri) relative to more conventional cases of glioblastoma." (PMID 38786045, 2024). "Moreover, CD47 antibody combined with alkylating chemotherapy has proved effective in glioblastoma." (PMID 39707188, 2024). "Exosomes with a targeted approach (e.g., CD47 targeting) have shown promising outcomes in solid tumors of deadly cancers, including GBM (glioblastoma), PDAC (pancreatic ductal adenocarcinoma), and TNBC (triple-negative breast cancer)." (PMID 36678782, 2023). "Interestingly, inhibition of glioblastoma HA synthesis with 4-methylumbelliferone (4MU) also led to downregulation of CD47 expression in glioblastoma cells and upregulated SIRPα expression in macrophages, which further facilitated the phagocytosis of glioblastoma cells by macrophages." (PMID 35410993, 2022). "Furthermore, we have found that the dendrimer itself influences various parameters of the cells such as the expression of surface markers PD-L1, TIM-3 and CD47, targets for immune recognition and other biological processes suggested to be regulating glioblastoma cell invasion." (PMID 35628503, 2022). "Therefore, accumulating evidences indicate that inducing M1-like TAMs polarization and targeting the CD47/SIRPα axis could uncover the clinical translational potential for glioblastoma treatment." (PMID 35410993, 2022). "Interestingly, CD47 knockdown using siRNA in U87 cell line induced a significant downregulation of UHRF1 indicating that CD47 positively controls the expression of UHRF1 in glioblastoma cells." (PMID 27839516, 2016). "To examine how IgG subclass may affect antibody-mediated cellular phagocytosis (ADCP) effects and CD47-Sirp disruption-induced phagocytosis, we treated glioblastoma cells with an IgG1-antibody against an unrelated target, epidermal growth factor receptor (EGFR, cetuximab)." (PMID 27092773, 2016).
glioblastoma (continued). "Anti-CD47 antibodies suppress tumor growth, enhance antitumoral macrophage recruitment, and activate CD8+ T cells in multiple tumor models, including glioblastoma, where CD47 blockade reprogrammed TAMs." (PMID 40936918, 2025). "In glioblastoma, CPT1A-derived acetylated acetyl-CoA supports NF-κB/RelA acetylation, which drives CD47 transcription and inhibits macrophage phagocytosis, thereby facilitating immune evasion." (PMID 41219902, 2025). "Researchers have developed an injectable hydrogel to co‐deliver macrophage‐targeting nanocarriers and CD47 antibodies into the postoperative tumor cavity of GBM, enabling in situ editing of local macrophages to generate CAR‐M capable of targeting and eliminating glioblastoma stem cells (GSCs)." (PMID 40395752, 2025). "In addition, CD47-targeting immune checkpoint inhibition can induce GBM cell death via Akt/mTOR inactivation and elevated autophagic flux in glioblastoma cell lines." (PMID 38890642, 2024). "In the expansion phase, subjects were enrolled into one of the five cohorts: recurrent glioblastoma (rGBM), pancreatic cancer, ovarian cancer, TNBC, and a high-CD36 and high-CD47 basket cohort." (PMID 39627379, 2024). "Most recently, c-Src was reported to bind and phosphorylate CD47 in an EGFR-dependent manner, which led to CD47 stabilization and immune evasion in a glioblastoma model." (PMID 37958404, 2023). "A study fused two different peptides (CDX or CREKA peptides) to the N-terminus of CD47, enabling specific targeting of U87 and GL261 glioblastoma cells, thus achieving a targeted effect on glioblastoma." (PMID 37946166, 2023). "In addition, CD47 expression levels in human glioblastoma (GBM) specimens correlate with EGFR and c‐Src activation and aggravation of human GBM." (PMID 37541303, 2023). "In glioblastoma multiforme, enhanced fatty acid metabolism by co-enhancement of CPT1A and CPT2 and immune checkpoint CD47, which functions as an anti-phagocytic signal, promotes the growth of radioresistant glioblastoma multiforme cells." (PMID 37601653, 2023). "Given the combined action of CD36 and CD47, a compound interfering with both receptors (VT1021, a cyclic pentapeptide) was tested for safety in solid tumors, including glioblastoma." (PMID 35054787, 2022). "This article reviews the feasibility of CD47/CD24 antibody treatment, either individually or in combination, to target the tumor stem cells and the antitumor immunity in glioblastoma." (PMID 34363319, 2021). "To evaluate whether phagocytosis modulation promotes antitumour immune responses against poorly immunogenic tumors, we first evaluated whether CD47 is expressed in human and mouse glioblastoma (GBM), a malignant brain tumor." (PMID 32198351, 2020). "Late-breaking studies reported that targeting CD47 by SIRPα-based fusion protein increased macrophage-mediated elimination of NSCLC and glioblastoma cells." (PMID 31829270, 2019). "Dissected tumors from human glioblastoma xenografted within NOD.Cg-PrkdcscidIl2rgtm1Wjl/SzJ mice and treated with anti-CD47 showed a significant increase of M1 macrophages within the tumor." (PMID 27092773, 2016). "Glioblastoma (GBM) acquires malignant traits through complex molecular adaptations that sustain immune evasion, often characterized by hypoxia and overexpression of the phagocytosis checkpoint CD47." (PMID 41620401, 2026). "Targeting both CD47 and CD36 simultaneously has led to the development of dual inhibitors like VT1021, a cyclic pentapeptide currently being evaluated for safety in solid tumours, including glioblastoma." (PMID 41195773, 2025). "In vitro analysis of mouse BMDM and peripheral blood-derived human macrophages have shown that the addition of anti-CD47 mAb enhances myeloid cell effector functions against glioblastoma cells regardless of the M1/M2 polarization status." (PMID 38786045, 2024). "The expression of CD47 is rare, suggesting that the CD47 and SIRPα protein interaction is not typical in newly diagnosed glioblastoma." (PMID 38786045, 2024).
glioblastoma (continued). "Although these pre-clinical studies targeting CD47 in glioblastoma have shown promise, there have been no clinical trials to date." (PMID 37857607, 2023). "These tracers target membrane proteins whose expression is altered in glioblastoma (including the EGFR, DLL4, EPHA2, CD47, AC133 antigen, and MT1-MMP): several components of the tumor microenvironment including vessels, macrophages, and extracellular matrix proteins." (PMID 35008238, 2021). "CD47 has been found to be highly expressed in GBM cells, especially glioblastoma stem cells." (PMID 33329583, 2020). "Furthermore, miR-149 is also downregulated in glioblastoma cells and has been proposed to act as a tumor suppressor by targeting RAP1B, CD47, CCN1, and NXF1." (PMID 23144691, 2012). "Relative to CD47, the expression of CALR may be more prevalent in glioblastoma." (PMID 38786045, 2024). "In glioblastoma multiforme (GBM) research, where drug delivery is constrained by the blood-brain barrier, BAMPA-O16B/siRNA liposomes have been able to effectively transport anti-CD47 and PD-L1 siRNA into intracranial GBM tumors in mice." (PMID 38545114, 2024). "A glioblastoma study employing a combinatorial treatment to target both VEGF and CD47, the latter of which inhibited the phagocytic effect of macrophages, revealed that it could trigger autophagy of cancer cells which attenuated the phagocytosis and cytotoxicity of macrophage population." (PMID 33605033, 2021). "We further propose that the local application of the anti‐CD47/anti‐CD24 antibodies, combined with CAR‐T, tumor vaccines, immune checkpoint inhibitors, or other systemic immunotherapies will likely improve the overall efficacy for clinical treatment of glioblastoma." (PMID 34363319, 2021). "High expression of CD47 has been shown to correlate with poor clinical outcomes in patients with hematological cancers such as non-Hodgkin lymphoma or acute myeloid leukemia (AML) and also in solid tumors (ovarian, glioblastoma, glioma, and others) and proposed to be a clinical prognostic factor." (PMID 29065481, 2017).
ovarian carcinoma (96 papers, 2008 to 2026). A malignant neoplasm originating from the surface ovarian epithelium. "In solid tumors such as ovarian cancer and non-small cell lung cancer, CD47 expression has been strongly associated with poorer prognosis and more aggressive disease due to its role in immune evasion." (PMID 40104289, 2025). "This study indicated that ovarian cancer stem-like cells are susceptible to phagocytosis by macrophages due to low CD47 expression." (PMID 38832992, 2024). "The differential gene expression in TCGA database also confirmed that the CD47 expression encoding gene was up regulated in ovarian cancer patients." (PMID 38832992, 2024). "It was found that the CD47 expression was relatively high in patients with endometriosis-associated ovarian cancer (EAOC) compared with the normal group." (PMID 38832992, 2024). "Compared to control, CD47 blockade therapy with SIRPa-Fc decoy receptor (TTI-621) enhanced macrophage-mediated in-vitro phagocytosis of ovarian cancer cells (BRCA1 mutated, UWB1.289 and its counter cell line with BRCA1 wild type, UWB1.289)." (PMID 37468567, 2023). "It was recently reported that CD47 expression is upregulated in ovarian cancer cells and associated with poor prognosis and the infiltration of CD163+ TAMs." (PMID 37876933, 2023). "CD47 is upregulated in many malignancies, and the first observations of cancer-associated CD47 overexpression were made in ovarian cancer." (PMID 37958404, 2023). "High expression of CD47 has been associated with poor prognosis in acute myeloid leukemia, ovarian cancer, and glioma." (PMID 37720221, 2023). "CD47 is highly expressed in ovarian cancer, and has been linked to worse clinical prognosis, including progression-free survival." (PMID 35565348, 2022). "Dual targeting tumor-associated glycoprotein 72 (TAG-72) and CD47 are effective in ovarian cancer model." (PMID 36275669, 2022). "CD47 was originally discovered as a tumor-associated antigen for ovarian cancer, but its pathophysiological significance was unclear." (PMID 33925464, 2021). "A study of ovarian cancer demonstrated that increased CD47 expression is associated with worse prognosis, increased migration and invasion, and the induction of epithelial-mesenchymal transition." (PMID 34944850, 2021). "In agreement with a previous study, we found that CD47 was highly expressed in ovarian cancer and was associated with poor clinical characteristics and prognosis." (PMID 28380460, 2017). "The results showed that surgical stage, CD44 expression, CD47 expression and c-met expression were independent risk factors for ovarian cancer prognosis." (PMID 25658794, 2015). "Furthermore, the overexpression of CD47 has been documented in various malignancies, including colorectal and ovarian cancers, and has been associated with adverse clinical features such as advanced tumor stage and poor differentiation." (PMID 40765033, 2025). "CD47 is commonly overexpressed in ovarian cancer patients and is associated with poor prognosis." (PMID 38832992, 2024). "Interestingly, dual CAR-T cells targeting two tumor antigens: TAG-72 (tumor-associated glycoprotein 72) and CD47, were recently generated and showed great benefit for ovarian cancer." (PMID 36429020, 2022). "Consistently, differential gene expression among TCGA showed a trend for both TSP-1 and CD47-encoding genes (i.e., THBS1 and CD47, respectively) to be upregulated in ovarian carcinoma patients, especially with elevated THBS1 mRNA expression in case of vascular and lymphovascular invasion." (PMID 34638503, 2021). "Intriguingly, the expressions of all immune checkpoint molecules in the high-risk group were greater than that of another group, except for CD47 (p < 0.05), suggesting that high-risk ovarian cancer patients might be more likely to benefit from immunotherapy." (PMID 35071242, 2021). "First, we found CD47 high expression associated DEGs in ovarian cancer." (PMID 34966389, 2021).